HIF1A (hypoxia inducible factor 1 subunit alpha)
Diseases named in the same sentence as HIF1A in open-access papers (continued):
Sharing a sentence is not in itself a finding about the gene and the disease.
tumor (continued). "In preclinical cancer models, CRISPR-mediated HIF-1α deletion has been shown to reduce tumor growth, inhibit angiogenesis, and enhance T cell-mediated immunity." (PMID 39981236, 2025). "These nanoparticles inhibit tumor growth and enhance chemotherapy efficacy by decreasing HIF-1α expression." (PMID 40136686, 2025). "It is a substantial challenge to understand how tumor cells exploit HIF-1α to orchestrate different responses to survive hypoxia." (PMID 40171017, 2025). "Development and use of small molecule inhibitors targeting HIF-1α to block the transcriptional activity responsible for angiogenic gene expression in the hypoxic tumor microenvironment." (PMID 40851994, 2025). "Specifically, MG modifies the transcriptional coactivator p300 and reduces its ability to bind to HIF-1α, thus limiting the function of HIF-1α to promote angiogenesis under hypoxic conditions and inhibiting nutrient supply to the tumor." (PMID 40352588, 2025). "Inactivation of SDH subunits leads to succinate accumulation, and succinate accumulation in tumor tissues stabilizes HIF-1α by inhibiting prolyl hydroxylases to promote angiogenesis and metastasis." (PMID 41488637, 2025). "The hypoxic tumor microenvironment further amplifies oxidative stress through HIF-1α–mediated pathways, thereby fostering aggressive growth and deepening immunosuppression." (PMID 41009025, 2025). "In summary, our results demonstrated that L-2-HG inhibited iron death in tumor cells by promoting HIF1A expression and further promoted the malignant phenotype of RCC cells." (PMID 41198650, 2025). "In contrast, in hypoxic tumor zones, HIF-1α binds to HREs and initiates the transcription of viral genes, enabling selective replication and oncolysis within the tumor." (PMID 40927720, 2025). "Future research should focus on elucidating the mechanisms by which HIF-1α inhibits exosome production and subsequently tumor progression." (PMID 40534881, 2025). "HIF-1α serves as an upstream regulator of numerous angiogenic factors, directly inducing the transcription of vascular growth factors and promoting tumor angiogenesis." (PMID 40813760, 2025). "Surprisingly, we detected no significant changes in the expression of HIF1A or other genes of the HIF1A pathway in both tumor and normal tissue samples collected from our patients before and after metformin intake." (PMID 40468055, 2025). "Under these extreme hypoxic conditions, HIF-1α functions to regulate the expression of several genes through multiple pathways to support tumor cell survival and growth." (PMID 41585262, 2025). "Hypoxic cells generally exhibit greater chemo- and radio-resistance compared to normoxic cells, with the activation of HIF-1α-related pathways contributing to increased resistance in tumor cells." (PMID 40861273, 2025). "For example, VEGF, upregulated by HIF-1α, is a central player in angiogenesis and also modulates immune responses within the tumor microenvironment." (PMID 40507229, 2025). "Research has shown that treatments like radiation therapy can increase tumor hypoxia, leading to elevated levels of both HIF-1α and SDF-1α, which in turn enhance the recruitment of macrophages to the tumors." (PMID 40867316, 2025). "The activity of HIF-1α in untreated control cells grew progressively as the tumour size increased because the expanding cell population experienced oxygen deficiency." (PMID 41463127, 2025). "These microenvironmental constraints can limit iron availability, activating adaptive pathways such as HIF-1α, which promotes metabolic adaptation and tumor invasiveness." (PMID 41190142, 2025). "HSP70 promotes HIF-1α SUMOylation under hypoxia, conferring ferroptosis resistance and tumor recurrence after ablation." (PMID 41306527, 2025). "This process results in HIF-1α transcriptional upregulation of PD-L1 expression, further promoting tumor immune evasion, which mitigates the cytotoxic effect of selective PFKFB3 inhibitors." (PMID 39897050, 2025).
tumor (continued). "Specifically, inflammasomes release IL-1β and IL-18, activating NF-κB and hypoxia-inducible factor 1-alpha (HIF-1α) signalling in the tumour microenvironment." (PMID 41148809, 2025). "This stabilisation of HIF-1α initiates diverse downstream signalling events that drive tumour progression and metastasis in PCa." (PMID 40806577, 2025). "Similar to the Luminal A subtype, a higher WWOX/HIF1A ratio in Luminal B tumours correlates with poor prognosis." (PMID 41007296, 2025). "Preliminary data support the prognostic utility of these biomarkers (41.4% for HIF-1α and 55.2% for c-Myc) for TNBC, being significantly associated with clinical parameters, including tumor size, histological grade, lymph node status, and TNM stage." (PMID 40710528, 2025). "The hypoxic tumor microenvironment is a significant trigger for HIF-1α overexpression, which regulates the hypoxic response in the tumor microenvironment." (PMID 40227577, 2025). "EVs derived from hypoxic tumor cells are often enriched in HIF-1α-dependent miRNAs, which play a key role in the acquisition of hypoxia tolerance, inducing HIF1α stabilization and angiogenesis, influencing autophagy, or targeting apoptosis." (PMID 39023664, 2025). "Conversely, the combined administration of hyperbaric oxygen and teniposide can abrogate the inhibitory effect of HIF-1α, thereby promoting a “hot” tumor." (PMID 40098962, 2025). "Autophagy-related gene BECN1 exhibits a positive correlation with HIF1α expression, indicating potential synergistic adaptation mechanisms that support cell survival within hypoxic tumor microenvironments." (PMID 41357522, 2025). "HA-RSCD/siRNA reduced HIF-1α expression in vitro and in vivo, alleviating hypoxia-induced tumor sensitivity and inhibiting vascular growth by 60%." (PMID 40169560, 2025). "Following vascular normalisation, the hypoxia level measured by the HIF-1α marker was reduced significantly in PAK1KD tumours." (PMID 41294859, 2025). "More importantly, the downstream effectors of the mTOR pathway, such as VEGF, and HIF-1α, which contribute to angiogenesis and tumor cell survival were also suppressed, leading to significant tumor inhibition following the combination treatment." (PMID 40604062, 2025). "The hypoxic microenvironment of GBM further promotes tumor progression through hypoxia-inducible factor 1-alpha (HIF-1α) activation and vascular endothelial growth factor (VEGF)-driven angiogenesis, enhancing invasion and limiting therapeutic efficacy." (PMID 40647449, 2025). "Intriguingly, tumor-derived exosomal miR-183-5p activates both HIF-1α and STAT3, establishing a link between hypoxic signaling and enhanced proteolysis." (PMID 40704145, 2025). "Hypoxic regions within tumor tissues were identified through HIF-1α immunostaining, visualized as green fluorescence." (PMID 40901943, 2025). "We crossed these mice with Hif1αf/f (Hif1α knockout [KO]), Hif2αf/f (Hif2α KO), and both Hif1αf/fand Hif2αf/f (Hif1α/Hif2α double KO [DKO]) mice to analyze tumor development in the kidneys." (PMID 39807625, 2025). "HIF-1α expression was assessed in tumor sections from all histopathologically confirmed OSCC cases, revealing overexpression in 30 cases (66.7%) and underexpression in 15 cases (33.3%)." (PMID 40546546, 2025). "We suggest that HIF-1α/VEGF signaling after the first sampling resulted in widespread angiogenesis in the tumor and damaged the liver." (PMID 40365190, 2025). "Tumours often adapt to low oxygen levels by upregulating HIF‐1α expression through metabolic reprogramming, thereby promoting tumour cell proliferation and metastasis." (PMID 40954549, 2025). "Vascular endothelial growth factor (VEGF) drives tumor angiogenesis through hypoxia-inducible factor 1α (HIF-1α)-mediated transcriptional regulation, a process amplified by oncogene signals, growth factors, and hypoxic stress." (PMID 40620671, 2025).
tumor (continued). "Lysyl‐oxidase like‐2 (LOXL2) can also interact with H3 histones, deacetylate H3K36 and block the transcription of H3K36 acetylation‐dependent genes, such as c‐myc and HIF1α, thereby inhibiting the growth of transplanted tumours in vivo." (PMID 39778006, 2025). "Plus, it has been shown that the delivery of small interfering RNA (siRNA) robustly blocks tumor cell progression by silencing the HIF-1α/CD73 axis." (PMID 40872479, 2025). "Research indicates that TIGIT cooperates with HIF1-α to enhance tumour cell invasiveness, colony formation and angiogenesis, and subsequently promotes tumour development and progression." (PMID 40994140, 2025). "TACE induces local hypoxia by blocking tumor blood supply, which activates HIF-1α and upregulates pro-angiogenic factors such as VEGF and PDGF." (PMID 41383585, 2025). "In the identification of novel hypoxia-responsive lncRNAs, novel lncRNAs such as RP11-390F4.3, which are HIF-targeted transcripts, have been shown to be directly activated by HIF-1α, driving tumor invasion by inducing EMT." (PMID 40861273, 2025). "Mechanistically, TFE3 activation upregulates phosphate cytidylyltransferase 1A (PCYT1A), driving phosphatidylcholine overproduction that activates the HSP90/HIF1A axis in tumor cells to enforce stemness." (PMID 40917018, 2025). "An elevated HIF-1α level promotes various biological processes like angiogenesis and metastasis in tumor cells." (PMID 40724929, 2025). "We established that the WWOX/HIF1A ratio orchestrates tumour immune responses, fundamentally shaping immune evasion, inflammation, and immune cell infiltration across cancers." (PMID 41007296, 2025). "HIF-1α and ROS are interrelated in this stress response, and tumor cells induce ROS production in response to PARP inhibitors." (PMID 39625235, 2025). "HIF-1α plays a pivotal role in facilitating tumor growth by adapting cellular and microenvironmental processes to low oxygen conditions." (PMID 39981236, 2025). "Factors such as HIF-1α are overexpressed in a hypoxic immune microenvironment, thereby aiding tumor immune evasion and promoting tumor growth." (PMID 40114928, 2025). "In CRC, FDFT1 functions as a tumor suppressor by negatively regulating the AKT/mTOR/HIF1α signaling pathway." (PMID 40145543, 2025). "To address this, we developed TNBCvax, a multi-antigen, multi-peptide vaccine targeting three tumor-associated antigens overexpressed in TNBC: TOP2A, HIF-1α and IGF-1R." (PMID 40969744, 2025). "Hypoxic tumour subvolumes, characterised by HIF-1a stabilisation and the upregulation of angiogenic factors like VEGF, are well-recognised mediators of radioresistance." (PMID 41226343, 2025). "The tumor suppressor miR-204 inhibits VM in TNBC by targeting HIF-1α and downstream signaling components, including PI3K/AKT, RAF1/MAPK, VEGF-A, and FAK/SRC pathways." (PMID 41400702, 2025). "We found that the WWOX/HIF1A expression ratio critically regulates oncogenic signalling pathways and cell proliferation across diverse tumour types." (PMID 41007296, 2025). "As tumours grow beyond 1–2 mm in diameter, the upregulation of HIF-1α increases to provide oxygen/nutrients to developing hypoxic areas." (PMID 40427172, 2025). "The tumor microenvironment frequently contains hypoxia, which can trigger the expression of HIF-1α, which can directly control the expression of MCT1 and MCT4." (PMID 40917751, 2025). "In CCA, overexpression of HIF-1α correlates with advanced tumor stage, increased tumor size, vascular invasion, and intrahepatic metastasis." (PMID 41425711, 2025). "HIF-1α plays a key role in cellular adaptation to the low-oxygen conditions of the tumor microenvironment." (PMID 40731797, 2025). "We identified some common transcriptional changes shared by all resistant samples, with IPA exhibiting activation of IL-8, HIF1α, cytokine/chemokine, tumor microenvironment, and phagosome formation pathways." (PMID 39910038, 2025).
tumor (continued). "Under hypoxic conditions, the interaction between tumor and immune cells activates the HIF-1α, NF-ĸB, and STAT pathways, enhancing the production and secretion of proinflammatory cytokines." (PMID 40244228, 2025). "Ultrasound disruption of OPMBs enabled the targeted release of oxygen and photosensitizers to the tumor, significantly improving tumor oxygenation and singlet oxygen production, inhibiting HIF-1α and related pathways, and blocking angiogenesis and EMT." (PMID 41472729, 2025). "In the case of HIF1A, a small decrease in its expression levels is observed in tumor tissue vs. normal tissue (0.07 times, p ≤ 0.05), in addition to its null effect on patient survival." (PMID 40072116, 2025). "In BC, tumor-derived exosomes contribute to doxorubicin resistance by stabilizing HIF-1α and delivering lncRNA H19 to adjacent cells, thereby reinforcing a resistant microenvironment." (PMID 40941035, 2025). "While preclinical studies initially demonstrated that HIF-1α inhibits CD8+ T cells and promotes the conversion of tumor-associated macrophages (TAMs) to the M2 phenotype, its effects on NK cells remained unclear." (PMID 40297580, 2025). "CSCs within the tumor niche are enriched by HIF1α which is also a key regulator of tumor angiogenesis." (PMID 40045186, 2025). "The discovery of HIF-1α helped researchers understand how hypoxic conditions promote tumor metabolic alterations, influencing tumor growth and metastasis." (PMID 40696413, 2025). "Overexpression of Myc stabilizes HIF1a, a transcription factor that drives the Warburg effect, leading to increased lactic acid production in tumor cells." (PMID 40330466, 2025). "HIF-1α can inhibit glutamine synthetase (GS), which leads to the impaired motility of cancer cells, thus achieving the effect of tumor suppression." (PMID 40696413, 2025). "In CRC, DKC1 promotes tumor angiogenesis and metastasis by directly activating HIF-1α transcription, with its high expression significantly linked to advanced TNM stage and poor prognosis." (PMID 41446042, 2025). "Preclinical studies indicate that PRMT1 inhibitors, when used in conjunction with platinum‐based drugs, exhibit a synergistic effect in inhibiting tumor growth or the HIF1α/P300 interaction inhibitor menadione." (PMID 41256732, 2025). "In macrophages, AMPK activation suppresses HIF-1a and NFkB to favor the generation of anti-tumor M1 macrophages." (PMID 39796781, 2025). "Radiation‐induced HMGB1 release drives tumor cell dedifferentiation into a stem cell phenotype via the TLR2/YAP/HIF‐1α signaling pathway, thereby accelerating tumor recurrence and metastasis." (PMID 41354099, 2025). "In contrast, the GCS-IO NPs group also exhibited a decrease in HIF-1α expression, suggesting partial alleviation of tumor hypoxia due to PTT." (PMID 40514659, 2025). "Under hypoxic conditions in the tumor microenvironment, stabilized HIF-1α upregulates VEGF expression, driving angiogenesis and enabling further tumor growth and progression." (PMID 40341988, 2025). "In contrast, poor prognosis tumours with low WWOX/HIF1A ratios activate pathways that promote aggressive tumour behaviour." (PMID 41007296, 2025). "HIF-1α has been shown to control T cell effector function and anti-tumor immune response in hypoxic T cells through its regulatory role on IFN-γ production, whereas HIF-1α deficiency leads to T cell resistance to immune checkpoint blockers." (PMID 41230345, 2025). "A hallmark of GBM is hypoxia, which triggers cellular responses, like microvascular proliferation and the expression of hypoxia-inducible factor 1 (HIF-1α), contributing to tumor progression and chemoresistance." (PMID 40277699, 2025). "(c) ROS generated by MCs contribute to EMT by inducing oxidative damage that disrupts epithelial integrity and by activating NF-κB and HIF-1α (hypoxia-inducible factor 1-alpha), both associated with EMT and tumor progression." (PMID 40871387, 2025).
tumor (continued). "Depending on the tumor type, FAT1 has been shown to function as both an oncogene promoting HIF1α expression, invasiveness, and inflammation in advanced tumors, as well as a tumor suppressor by inhibiting Wnt signaling and tumorigenesis." (PMID 40458731, 2025). "HIF-1α fosters the upregulation of genes involved in tumor proliferation, invasion, and angiogenesis, thereby augmenting GBM growth and metastasis." (PMID 39781344, 2025). "The regulation of MICA and MICB by HIF-1α and metalloproteinases is of great significance for understanding tumor progression and molecular targeting." (PMID 40563539, 2025). "Hypoxia-inducible factor 1-alpha (HIF-1α) is a master transcriptional regulator that enables tumor cells to adapt to both hypoxia and oxidative stress." (PMID 40867898, 2025). "Beyond its direct effects on tumor cells, HIF-1α profoundly influences the IVM by fostering an immunosuppressive environment." (PMID 39981236, 2025). "HIF-1α serves as both a driver of tumor progression and a mediator of immune suppression, making it a critical target for therapeutic intervention." (PMID 39981236, 2025). "Beyond cytokines, metabolic factors such as tumor-derived lactate drive TAM polarization toward immunosuppressive phenotypes by activating pathways like hypoxia-inducible factor 1-alpha (HIF-1α)." (PMID 40330466, 2025). "Hypoxic tumor areas increase tumor aggressiveness, stemness, and resistance to treatment by inducing EMT via HIF-1α and associated pathways." (PMID 40556662, 2025). "In LGG, pathways associated with a good prognosis include oxidative phosphorylation (LHPP, PPA1, CYC1), supported by a high WWOX/HIF1A ratio, which improves energy metabolism and reduces tumour aggressiveness." (PMID 41007296, 2025). "HIF-1α is crucial for cellular adaptation to the low oxygen levels frequently encountered in the tumor microenvironment." (PMID 41311849, 2025). "KRAS gene can stimulate the production of CSF2 and lactic acid in tumor cells by stabilizing HIF-1α in human colorectal cancer specimens." (PMID 40297580, 2025). "inhibits tumor angiogenesis in vitro and in vivo by suppressing HIF-1α/VEGF through the Akt/mTOR/phospho-p70 S6 kinase (p70S6K) signaling pathway, thereby exerting cancer-suppressive effects." (PMID 41585262, 2025). "Given that HCC is a solid tumor characterized by severe TME hypoxia, however, the teniposide-induced activation of the cGAS-STING pathway is significantly inhibited by hypoxia-inducible factor 1α (HIF-1α), thus contributing to a “cold” tumor." (PMID 40098962, 2025). "The laboratory analysis of tumor tissue, conducted through immunohistochemistry,revealed the expression levels of HIF-1α and HIF-2α." (PMID 40636217, 2025). "In contrast, the hypoxia-responsive nanocore formulation (HDiR@D-TT) demonstrated marked colocalization between DiR and HIF-1α signals, confirming preferential accumulation within hypoxic tumor compartments." (PMID 40901943, 2025). "HIF-1α is another key regulator, promoting angiogenesis and vascular remodeling, which upregulates glucose transporters and glycolytic enzymes to support tumor metabolism." (PMID 39857281, 2025). "Hypoxia, due to poor vascularization, further promotes tumor growth and immune evasion, partly by stabilizing HIF-1α in TAMs, leading to the secretion of matrix-degrading enzymes and pro-tumor factors." (PMID 40940995, 2025). "The expression of HIF1A was negatively correlated with tumor purity (P < .05), suggesting that HIF1A was highly expressed in the gastrointestinal cancers microenvironment." (PMID 39928794, 2025). "We observed a reduction in HIF1A expression within tumor tissue compared to surrounding tissue at the mRNA and protein levels, with a third of all tumor RCC samples showing very low or no HIF1A expression." (PMID 40332447, 2025).